IL1B (interleukin 1 beta)
Diseases named in the same sentence as IL1B in open-access papers (continued):
Sharing a sentence is not in itself a finding about the gene and the disease.
acute kidney injury (continued). "Notably, cancer-induced hyperuricemia, hyperkaliemia, acute kidney injury (AKI), anorexia, sarcopenia, and high systemic levels of TNF-α, IL-1β, IL-6, and IL-18 can impair heart function, induce myocardial fibrosis and cardiomyocyte atrophy." (PMID 39200115, 2024). "Moreover, the marked anti-inflammatory actions of linagliptin have been characterized in an endotoxin-induced acute kidney injury model, where DPP-4 inhibition inhibited NF-κB pathway and the downstream pro-inflammatory cytokines IL-1β and TNF-α." (PMID 35890148, 2022). "Moreover, studies in vivo using a model of LOCBE-induced acute renal failure pointed out that kidneys of envenomed rats presented increased levels of superoxide, NO, MMPs and an excessive amount of proinflammatory cytokines such as TNF-α and IL-1β." (PMID 34209394, 2021). "A study of the acute renal failure mouse model showed that MSC administration could increase the recovery of renal function through the inhibition of production of proinflammatory cytokines, such as IL-1β, TNF-α, and IFN-γ." (PMID 31611920, 2019). "Knowing that both circulating and tissue cytokines are important in triggering acute kidney injury induced by cisplatin, we analyzed serum levels and tissue expression of the main cytokines and observed lower serum levels of TNF-α and IL-1β in the CR group than in exercise group." (PMID 28303105, 2017). "In addition, the role of proinflammatory cytokines in cisplatin-induced acute renal failure has been well documented, and elevation of the proinflammatory cytokines TNF-α and IL-1β as well as that of IL-6 has been demonstrated in humans with acute renal failure." (PMID 24171038, 2013). "Similarly, ALA alleviated acute kidney injury (AKI) in CLP rats by inhibiting NF-κB; downregulating proinflammatory cytokines (TNF-α, IL-6, IL-1β), iNOS, and HMGB1 expression in renal tissues; and reducing serum blood urea nitrogen (BUN) and creatinine levels." (PMID 40699721, 2025). "In LPS treated renal tubular epithelial NRK-52E cells (AKI), emodin also inhibited LPS-induced TLR2, NF-κB, TNFα, IL-1β and IL-6 expression in vitro, which may contribute to the immune regulation of emodin in LPS-induced acute kidney injury." (PMID 35744949, 2022). "In cisplatin-induced nephrotoxicity, increased expression of IL-1β was detected, which triggered the activation of IL-1R, inducing TNF-α production and leading to AKI, suggesting that knocking out IL-1 receptor holds the potential of decreasing cisplatin-induced acute kidney injury." (PMID 36552226, 2022). "Overexpressed PVT1 can enhance the expression of IL-6 and IL-1β in a nonbinding manner by regulating the nuclear factor-κB (NF-κB) pathway, which is considered a critical mechanism in the regulation of immune and inflammatory processes, and ultimately aggravating septic acute kidney injury." (PMID 31304055, 2019). "Finally, in an LPS-induced acute kidney injury (AKI) model, MLN4924 attenuates renal inflammation by inactivating CRL1 and subsequent NFκB inactivation, leading to reduced production of pro-inflammatory cytokines (TNF-α, IL-6, and IL-1β) upon LPS stimulation in renal tubular cells." (PMID 38434245, 2023).
dementia (75 papers, 2012 to 2026). Loss of intellectual abilities interfering with an individual's social and occupational functions. "Although the exact causes of dementia remain multifactorial and complex, oxidative stress (reactive oxygen species), neuroinflammation (TNFα, IL-6, and IL-1β), and inflammasomes are considered central mechanisms in its pathology." (PMID 40277934, 2025). "Given the massive public health burden of dementia and delirium, both of which have been associated with IL-1, it is important to characterise differential roles of IL-1β in these processes." (PMID 29875474, 2019). "Overexpression of pro-inflammatory cytokines, particularly IL-1β, has shown to significantly affect spatial memory tasks and, is associated with both dementia and delirium." (PMID 30618722, 2018). "Several population-based studies have shown that peripheral inflammatory cytokines, especially IL-6, TNFα, and IL-1β, are correlated with the risk of dementia." (PMID 27340344, 2016). "A logistic regression model was built to adjust for the effect of the presence of prior dementia on the association between CSF IL-1β level and delirium status." (PMID 25124807, 2014). "Furthermore, MAP improved inflammatory biomarkers such as CRP, IL-6 and IL-1β, showing its potential to target biological pathways associated with dementia." (PMID 40563752, 2025). "Additionally, elevated TNFα and IL-1β have been observed in the CSF of PLWH with HIV-associated dementia (HAD), two cytokines with the capacity to both induce neuronal injury via release of neurotoxic molecules, including ceramide and L-cysteine." (PMID 40588746, 2025). "There may be a common role for IL-1β in the pathogenesis of all these neurodegenerative causes of dementia." (PMID 32968032, 2020). "Importantly, the results of the logistic regression analysis suggest that CSF IL-1β remains associated with delirium after adjusting for the presence of prior dementia." (PMID 25124807, 2014). "It is of interest that PTX3 has recently been associated with dementia progression and whether the latter is linked to its synthesis downstream of IL-1β merits investigation." (PMID 23840908, 2013). "In addition, inhibiting the expression of TLR4, a receptor on microglia, reduces microglial activation and the release of inflammatory cytokines, including IL-6, TNF-α, and IL-1β, alleviating the chronic neuroinflammation associated with AD and other dementias." (PMID 40872491, 2025). "Adults with HIV-associated dementia have been found to have decreased levels of neurogranin in the frontal cortex, which at least to some extent, may be mediated by the proinflammatory cytokines IL-1β and IL-8." (PMID 30649659, 2019). "Moreover, it has recently been shown that IL-1β is causative and synergises with cyclo-oxygenase 1-mediated prostaglandins to induce acute working memory deficits in an animal model relevant to delirium during dementia." (PMID 25124807, 2014). "mRNA of both cytokines TNF‐α and IL‐1β showed significant up‐regulation in HAD brains compared with non‐dementia HIV/AIDS patients." (PMID 38282400, 2024). "This confirmed the role of the inflammasome pathway and upregulation of IL-1β in pre-dementia patients." (PMID 37445700, 2023). "Among inflammatory genes, polymorphisms in IL1B and TNF showed a protective function in the development of dementia or AD, while MIR146A was associated with CSF biomarkers." (PMID 36829875, 2023). "In the present study, the effect of IL1B, MIR146A and TNF on dementia or AD susceptibility confirmed previously published data." (PMID 36829875, 2023). "Several studies have found increased levels of pro-inflammatory cytokines and proteins like interleukin-6 (IL-6), interleukin-1β (IL-1β), C-reactive protein (CRP), or α1-antichymotrypsin (α1-AT) to be associated with the onset of all-cause dementia." (PMID 36085081, 2022).
dementia (continued). "The D. salina-zeaxanthin was demonstrated to mitigate the D-galactose-induced aging dementia in rats by decreasing the brain level of IL-1β and iNOs." (PMID 36290351, 2022). "There is a growing body of evidence that both local and systemic inflammation are important in dementia, our present data also demonstrated that Gao-Zi-Yao exerts regulation effects on systemic inflammation by decrease of IL-1β, IL-2 and." (PMID 35643519, 2022). "It is widely acknowledged that NLRP3 inflammasome activation contributes to DM and dementia by triggering IL-1β maturation." (PMID 32425784, 2020). "It has been found that the levels of inflammation-related markers, such as IL-1β, IL-18, and IL-6, are increased in both DM and dementia patients." (PMID 32425784, 2020). "CCH-induced production of IL-1β, which is mediated by the NLRP3 inflammasome activation in the hippocampus, is a key pathological mechanism underlying dementia." (PMID 31766248, 2019). "Incident dementia was associated with increases in all five serum cytokines during the follow-up, and the strength of the significance remained for TNF-α, IL1-α, and IL-1β after applying the Bonferroni correction." (PMID 30510525, 2018). "Two other studies have revealed that IL-1β-31T is involved in inflammation-related lower cognition and is driven by a dementia process." (PMID 26937653, 2016). "Six of the eight (75%) dementia patients were CSF IL-1β positive and the other two had levels below 1 pg/ml but were detectable (0.32 and 0.66 pg/ml)." (PMID 25124807, 2014). "Neuronal induction of COX-2, leading to increased release of its product PGE2, is strongly stimulated by IL-1β, and has been linked to neuroinflammatory aspects of neurodegenerative diseases such as AD and HIV-associated dementia." (PMID 22642771, 2012). "Persistent microglial activation releases cytokines such as IL-1β and TNF-α, creating a neuroinflammatory milieu that drives the synaptic dysfunction and oxidative stress—processes implicated in both MS neurodegeneration and various dementias." (PMID 41602975, 2026). "In dementia, only IL‐1β showed a marginal significant increase (p = 0.08)." (PMID 41164885, 2025). "White matter hyperintensities (WMH), which are related to a synergy between IL1β and injury response, could be induced by endothelial cell activation, inflammation, and ischemic injury of the brain, as well as aging and dementia." (PMID 39109268, 2024). "With that in mind, our results add to the importance of IL1B genetic variability in AD or dementia." (PMID 36829875, 2023). "In addition, IL-1β is highly relevant to hypoperfusion-induced dementia by impairing oligodendrocyte progenitor cells and thus lead to white matter injury." (PMID 30662512, 2018). "An alternative hypothesis is that the combination of pre-existing dementia and subsequent hip fracture brought about CSF IL-1β production." (PMID 25124807, 2014). "IL-1β was found to be elevated in 75% of those with dementia in the current study, although importantly all of the patients had also suffered hip fracture, which would be predicted to drive IL-1β expression in the brain, particularly in those with prior CNS pathology." (PMID 25124807, 2014). "CSF IL-1β remained significant after adjusting for prior dementia status." (PMID 25124807, 2014). "Furthermore, interleukin-1 receptor antagonist (IL-1ra) has been shown to block LPS-induced working memory deficits and systemically administered IL-1β is sufficient to induce similar deficits in an animal model of delirium during dementia." (PMID 25124807, 2014). "Furthermore, we analyzed the association between IgG N-glycome and markers of inflammation including anti-inflammatory (IL-4 and IL-10) as well as proinflammatory factors (CRP, TNF-α, IFN-γ, IL-1β, and IL-6), contributing to explain the role of IgG glycosylation on dementia." (PMID 33542243, 2021).
dementia (continued). "Consistently, elevated peripheral pro-inflammatory cytokines (IL-1β, TNF-α, IL-2) have been reported in dementia patients." (PMID 41291751, 2025). "In clinical and pre-clinical models of dementia and AD, neuroinflammatory mediators such as the COX enzyme and pro-inflammatory cytokines, including TNF-α, IL-6, IL-1α, and IL-1β, trigger the nervous system’s inflammatory responses." (PMID 36840284, 2023). "In postmortem study performed in patients with severe dementia significantly elevated mRNA for IL-6 and TGF-β1 levels in the entorhinal cortex as compared with cognitively normal subjects was reported, whereas IL-1β mRNA was very low." (PMID 31129771, 2019). "Decreased in patients with dementia. miR-223 level correlated with Mental State Examination (MMSE) scores, Clinical Dementia Rating (CDR) scores, magnetic resonance spectroscopy (MRS) spectral ratios, and serum concentrations of IL-1b, IL-6, TNF-α, and CRP." (PMID 40943171, 2025). "Recently, the results of an animal study showed that hypoxia induces AD-like dementia symptoms, e.g., memory dysfunction via the dysregulation of seladin-1 and Tuj1 in the hippocampal region correlated with enhanced serum levels of TNF-α and IL-1β." (PMID 37605722, 2023). "Not only the APP gene is responsible for dementia in DS, GATD3A, SOD1, ERG, BACE2, DSCR1/RCAN1, APOE (19q13.32), BACE1 (11q23.3), IL1B (2q14.1), GSAP (7q11.23), UBB (17p11.2), and IRS1 (2q36.3) genes may also play a major role in dementia in DS." (PMID 35676933, 2022). "IL1B, TNFA, and TGFB1 mRNA levels were significantly higher in sPDD versus the other groups, confirming that also in our cohort, disrupted cytokine signaling correlates with the progression of PD to dementia." (PMID 34234281, 2021). "The involvement of cytokines in dementia is supported by studies showing that the levels of pro-inflammatory cytokines [e.g., tumor necrosis factor alpha (TNF-α), interleukin (IL)-1α, IL-1β, IL-6, and IL-8] are altered." (PMID 30510525, 2018). "Meanwhile, we investigate the associations between IgG N-glycan profiles and inflammation factors including anti-inflammatory (IL-4 and IL-10) and proinflammatory factors [IL-1β, IL-6, CRP, TNF-α, and interferon-gamma (IFN-γ)], which may further explain the role of IgG glycosylation in dementia." (PMID 33542243, 2021). "Interestingly, the brains of individuals resilient to dementia despite robust Alzheimer’s neuropathology (amyloid plaques and neurofibrillary tangles) displayed lower numbers of CD68+ microglia in the temporal lobe and higher levels of the cytokines IL-6, IL-1β, IL-1073." (PMID 32917850, 2020). "Unexpectedly, inflammatory markers, CRP, IL-1β, IL-6, and TNF-α did not discriminate dementia cases from non-cases." (PMID 37605096, 2024). "Our findings highlight the upregulation of several functionally immune-related proteins in dementia, such as IL17D, IL17C, IL17RB, and IL1B, among which IL17D also showed a strong negative correlation with cognitive performance." (PMID 37175824, 2023).
E. coli infection (75 papers, 2013 to 2025). "By detecting the mRNA levels of multiple cytokines in macrophages, we found that E. coli infection caused a sharp increase in the expression of Il-1β, TNF-α." (PMID 37644526, 2023). "Our findings are in agreement with these observations: the reduction in mtDNA caused by NAC, BAPTA-AM, or 2-APB during E. coli infection also reduced the expression of inflammatory factors IL-1β and IL-18." (PMID 36430657, 2022). "An increase in IL-1β levels due to Escherichia coli infection leads to defects in contextual fear conditioning, with loss of memory prevented by IL1Ra." (PMID 28347403, 2017). "Additionally, CVB3 infection increased the susceptibility of mice to Escherichia coli infection by decreasing IL-1β production." (PMID 37243164, 2023). "E. coli infection caused an acute suppurative inflammation in the lung with increased lung index and serum TG and TC contents; elevated pulmonary tumor necrosis factor-α, interleukin (IL)-1β, IL-6, IL-8, and leptin levels; and oxidative stress in mice." (PMID 30250258, 2018). "This indicates that while both LD4-PP and E. coli infection trigger IL-1β release, treatment with LD4-PP is able to alleviate the overstimulation of uroepithelial cells." (PMID 41415272, 2025). "After 9 h, PGD2 treatment significantly increased TNF-α, IL-1β, IL-6, and IL-8 levels compared to the E. coli infection group, while IL-10 levels decreased." (PMID 40874199, 2025). "We also administered the IL-1 receptor antagonist anakinra to competitively inhibit the function of IL-1β in vivo or, alternatively, used an anti-IL-1β antibody to neutralize IL-1β during E. coli infection." (PMID 40359428, 2025). "Comparative studies of wild-type and NLRP3−/− mice showed that after the challenge with LPS or E. coli infection NLPR3 deficient animals had significantly lower liver damage, associated with a diminished IL-1β production by macrophages." (PMID 40141330, 2025). "E. coli infection increased the expression of pro-inflammatory cytokines (Il-6 and Il-1β, all p<0.05) in leukocytes from MLN (control mice)." (PMID 38728303, 2024). "For the “Pathogenic Escherichia coli infection” pathway, the study recognized some important inflammatory factors, such as TNF-α, IL‐1β, IL‐1, IL‐8, and NF‐κb, which were associated with different signaling pathways." (PMID 36798127, 2023). "COX-2 inhibition also had impact on the inflammasome mediated IL-1β expression in response to uroepithelial E. coli infection." (PMID 37697284, 2023). "Compared to mice infected with E. coli alone, mice infected with CVB3 following E. coli infection showed significantly higher bacterial counts but much lower IL-1β levels in the peritoneal lavage fluid." (PMID 37243164, 2023). "Our results showed that NLRP3, caspase-1, GSDMD, and IL-1β were significantly upregulated in response to E. coli infection, with KEGG enrichment revealing that upregulated genes were mainly concentrated in the NOD-like receptor signaling pathway." (PMID 37511208, 2023). "In pigs, increased expression of pro-inflammatory cytokines IL-1β and IL-6 after Escherichia coli infection have been found, which was demonstrated to trigger mucin release and MUC gene expression." (PMID 34072321, 2021). "A study comparing S. aureus and E. coli infections demonstrated that IL-1β released during S. aureus was less when compared to E. coli infections." (PMID 33322651, 2020). "Previous studies have shown that the release of these cytokines, such as TNF-α, IL-6, and IL-1β, was induced by LPS during Escherichia coli infection." (PMID 33134350, 2020). "In this study, SeMet inhibited E. coli-induced protein expression of TNF-α and IL-1β, indicating that SeMet suppressed inflammation induced by E. coli infection in bMECs and macrophages and inhibited the cytokine storm." (PMID 32733409, 2020).